DLL4 (delta like canonical Notch ligand 4)
Diseases named in the same sentence as DLL4 in open-access papers (continued):
Sharing a sentence is not in itself a finding about the gene and the disease.
tumor (continued). "Indeed, certain xenografts that are resistant to anti-VEGF therapy are reported to be sensitive to anti-Dll4, and combination treatment with anti-VEGF and anti-Dll4 has additive effects on tumour growth." (PMID 19844231, 2009). "Assessing which patients express Dll4 in their tumour endothelium may be critical in predicting response to new therapies that target Notch or VEGF signalling." (PMID 19844231, 2009). "Anti-DLL4 antibodies have been reported to reduce tumour size in multiple tumour xenograft models and could also be therapeutically relevant in KS treatment." (PMID 19816565, 2009). "For these reasons, Dll4 is now recognized as a potential therapeutic target for tumor angiogenesis." (PMID 20016694, 2009). "Jagged1 antagonizes Dll4 during sprouting angiogenesis, and overexpression of Jagged1 in tumor cells has been shown to enhance neovascularization and tumor growth; however, the role of Jagged1 in pathological angiogenesis (including tumor angiogenesis) is not yet fully understood." (PMID 20016694, 2009). "In addition, the tumour vessels in this model showed dramatic disorganisation and dysfunction following Dll4-Notch blockade." (PMID 18827808, 2008). "An interesting approach might be to consider whether Dll4 blockade is sensitising tumour vessels to VEGF blockade or vice versa." (PMID 18827808, 2008). "Conversely, the levels of Dll4 expression in tumours correlate with the levels of VEGF expression." (PMID 18827808, 2008). "The factors produced by the tumour or expressed within the tumour vessels that confer sensitivity to Dll4-Notch blockade are unknown." (PMID 18827808, 2008). "However, strikingly, blockade of Dll4-Notch resulted in a growth inhibition in a variety of established human and rodent tumour models." (PMID 18827808, 2008). "In contrast to PPARβ/δ,however, Dll4 is essential not only for tumor angiogenesis but also forembryonic vascular development and arteriogenesis, and there seems to be no cross-talk orinteraction between both the PPARβ/δand Notch/Dll4 pathways." (PMID 18497874, 2008). "Local or systemic treatment of mice with Dll4-Notch inhibitors caused overgrowth of a non-functional tumour vasculature." (PMID 18827808, 2008). "Similarly, elevated Dll4 signals in vessels of cancers like breast and bladder suggest a role in suppressing excessive vascular proliferation, reducing vessel numbers, and promoting luminal expansion to enhance tumor cell blood supply." (PMID 40486870, 2025). "Furthermore, blockade of the DLL4 signaling may sensitize tumor cells to chemotherapy and immunotherapy in TNBC with TTN inactivation." (PMID 41326912, 2025). "Our results showed that observation of subtle differences in vasculature structure and perfusion patterns characterized by ICG time kinetics could be used to differentiate between inherited tumor vascular microenvironment differences, such as Dll4 expression levels." (PMID 36900252, 2023). "We hypothesize that the observation of subtle differences in vasculature structure and perfusion patterns characterized by ICG inflow and outflow using DE-NIR imaging could be used to differentiate between inherited tumor vascular microenvironment differences, such as Dll4 expression levels." (PMID 36900252, 2023). "Additionally, tumor-released exosomes may also transfer DLL4 to activate Notch receptors on ECs at distant sites, so there are several possibilities of how tumors change the endothelial transcriptome across large distances in the body." (PMID 37749321, 2023). "The SS.BN3IL2Rγ− CXM strain with low-level expression of Dll4 (referred to as Dll4−) had significant tumor growth inhibition compared with the parental SSIL2Rγ− strain with higher expression of Dll4 (Dll4+), despite a paradoxical increase in tumor blood vessel density in Dll4+." (PMID 36900252, 2023).
tumor (continued). "Besides, ABL001 (VEGF × DLL4), with enhanced biological anti-tumor activity in xenograft models than VEGF or DLL4 monoclonal therapeutic antibodies alone, is under phase 1 clinical study to evaluate combination therapy effect with heavy chemotherapy (NCT03292783)." (PMID 36389699, 2022). "In addition, tumor size could be predicted with 62% specificity and sensitivity using DLL4 (AUC = 0.62, p = 0.02)." (PMID 35681234, 2022). "Since metastasis is significantly reduced after knock-out of DLL4, this could be interpreted as mainly due to an inhibition of EMT (and thus Notch-linked), or alternatively due to a reduction of the number of circulating tumor cells." (PMID 33430387, 2021). "First, we showed that DLL4 was a potent stimulator of Notch1 signaling mainly in NOTCH1-mutated CLL cells, leading to the activation of some protumor genes and inducing processes that confer aggressiveness to the tumor, such as cell proliferation, migration, and angiogenesis." (PMID 31616059, 2020). "Interestingly, the same study found that both endothelial and tumor cells, that in that case also expressed Dll4, were capable of producing Dll4-bearing exosomes and that exosomal Dll4 was being incorporated into cells rather than signaling from exosomes to tumor or endothelial cells." (PMID 33198378, 2020). "In support of this hypothesis two recent studies showed that a loss of delta-like 4 (Dll4) increased in non-functional and convolute vessels, thereby reducing tumor growth." (PMID 31637217, 2019). "The Dll-4 protein molecule is encountered in physiological and pathological angiogenesis; Dll-4 protein serves as a negative regulator in tumorigenesis and as a positive regulator in tumor progression; the explanation of this duality of action still remains a mystery." (PMID 30111989, 2018). "Besides, Dll4 expression was identified in malignant cells of different types, and the ligand was shown to have an impact on colon cancer stem cell frequency by suppressing apoptosis of tumor cells." (PMID 28288569, 2017). "By reducing endothelial sensitivity to VEGF, these results imply that Dll4/Notch stimulation in tumor microenvironment could be beneficial to solid cancer patient treatment by reducing primary tumor size, improving tumor drug delivery and reducing metastization." (PMID 28288569, 2017). "Additionally, the role of Dll4 has been studied on tumor stem cells." (PMID 28086833, 2017). "Therefore, Dll4/Notch inhibition may also negatively affect the tumor stem cell populations through Atoh1 derepression-mediated upregulation of the CDK inhibitors Cdkn1b and Cdkn1c." (PMID 28086833, 2017). "Therefore, Dll4 deletion inhibited the intestinal tumor growth by inducing a dysfunctional and immature angiogenesis that led to hypoxia and therefore apoptosis as previously reported in other tumor models." (PMID 28086833, 2017). "In addition, the upregulation of Dll4-Notch signaling components has been implicated in tumor angiogenesis but not in tumor growth." (PMID 28157712, 2017). "We hypothesize that SYNJ2BP sustains DLL4 to suppress tumor growth and metastasis in human HCC." (PMID 27440153, 2016). "However, little is known about the regulation of Dll4/Notch in tumor angiogenesis." (PMID 26755662, 2016). "Dll4 is a Notch ligand that is induced in endothelial tip cells of angiogenic sprouts and loss of expression has been shown to lead to excessive production of aberrant non-functional tumor vessels and associated reduced tumor growth." (PMID 25393540, 2014). "Furthermore, inhibition of Dll4-Notch has been shown to result in tumor growth inhibition associated with the formation of a non-functional, hypersprouting tumor vasculature." (PMID 25364440, 2014). "Interestingly, DLL4-Notch signaling was reported to mediate tumor resistance to anti-VEGF therapy." (PMID 24931473, 2014). "However, the exact role of Dll4 in tumor growth and its potential in anti-cancer therapy remain unclear." (PMID 23967403, 2013).
tumor (continued). "Moreover, stromal DLL4 expression also correlated with tumor spread." (PMID 23898884, 2013). "Thus, high Dll4 expression should theoretically lead to fewer but larger vessels, and Dll4 overexpression or inhibition may consequently impair tumor angiogenesis." (PMID 23064377, 2013). "Moreover, as determined by staining tumor frozen sections with hypoxiprobe (which labels hypoxic tumor areas), tumors with Dll4+/− BM-VPC had significantly greater proportion of hypoxic areas, which strongly suggests that the vessels in these tumors were less functional." (PMID 21483741, 2011). "Therefore, DLL4 blockade may impair the remodeling of the tumor vasculature to become more mature and stable, resulting in increased vulnerability of tumor vessels to VEGF blockade." (PMID 21824400, 2011). "Therefore, the Dll4 expression levels might be considered as a general marker for vascular responses, such as during tumor angiogenesis or vascular remodelling events." (PMID 21483741, 2011). "Notch ligands other than Dll4 may also affect tumor angiogenesis." (PMID 21923938, 2011). "In addition to the anti-angiogenic mechanism of action of disrupting Dll4 in the tumor vasculature, direct effects on the frequency of tumor initiating cells (cancer stem cells) and tumor growth have been described for tumor cell-specific targeting of Dll4 alone or in combination with chemotherapy." (PMID 21923938, 2011). "Indeed, anti-DLL4 in combination with chemotherapy shows enhanced anti-tumor activity in preclinical tumor models despite the concern that reduced perfusion of tumor vessels might interfere with the delivery of therapeutic agents." (PMID 21824400, 2011). "Interestingly, a recent study has suggested that DLL4 blockade may reduce tumor-initiating cell frequency in certain xenograft models." (PMID 21824400, 2011). "In addition, Real and collaborators have recently showed that transplantation of bone marrow-derived vascular precursor cells with decreased Dll4 into tumor-bearing mice resulted in the formation of unstable vessels, as evidenced by the reduced pericyte coverage and reduced Fibronectin expression." (PMID 22087289, 2011). "However the precise mechanisms underlying the rapid reduction of tumor perfusion following Dll4-Notch inhibition are not fully understood." (PMID 21923938, 2011). "However, it is still unclear whether Dll4 is only expressed on tumor vessels or other cell types, and what role it plays during angiogenesis." (PMID 21483741, 2011). "Consequently, a putative role for Dll4 in tumor angiogenesis has been under intense scrutiny." (PMID 21483741, 2011). "However, based on the specific role of Dll4-Notch1 in neovascularization, anti-Dll4, and similarly anti-Notch1 and anti-Notch2 antibodies have been proposed as sharper therapeutic agents devoid of side effects against various tumor types in mouse xenograft models." (PMID 21078177, 2010). "Disruption of Dll4 signalling by overexpression or inhibition of Dll4 may impair tumour angiogenesis, and blockade of Dll4–Notch signalling results in an increased density of non-functional vasculature and is associated with a reduction in the growth of human xenografts." (PMID 19844231, 2009). "Moreover, defining the context of Dll4 expression, in terms of known markers of hypoxia and angiogenesis, may identify subgroups of tumours with distinct clinical behaviour and response to treatment." (PMID 19844231, 2009). "In addition, endothelial expression of Dll4 was negatively associated with nuclear HIF-2α expression by tumour cells, but this association was not significant after correction for multiple testing." (PMID 19844231, 2009). "Thus, the high levels of Dll4 expression on tumour vessels may be a result of relatively high levels of VEGF signalling in these vessels compared to most normal vessels." (PMID 18827808, 2008).
tumor (continued). "Among 16 natural compounds evaluated, isoxanthohumol (IXN), a prenylated flavanone, emerged as the most potent, suppressing both hypoxia-induced HIF-1α accumulation in tumor cells and VEGF-induced DLL4 expression in endothelial cells." (PMID 41683994, 2026). "Notch1, Notch4 and ligands (DLL4, JAG1) are overexpressed in >70 % of HCC cases and related to advanced tumour stage and vascular invasion." (PMID 41476776, 2026). "Neutralizing mAbs targeting Notch receptors or ligands, such as delta ligand-4 (DLL4), have also been developed to block Notch signaling and were reported to reduce colorectal CSC self-renewal and tumor growth in vivo." (PMID 40076613, 2025). "Delta-like ligand 4 (DLL4) and VEGF A play an essential role in angiogenesis and tumor vascularization in the TME." (PMID 40565299, 2025). "We implanted DLL4 overexpression and knockdown PDX cell lines subcutaneously into T/B-deficient nude mice to investigate whether DLL4 affects TNBC development in TTN-deficient mice, and tumor burden was limited by DLL4 expression in PDX1/PDX2 regardless of TTN genotype." (PMID 41326912, 2025). "High expression of NOTCH2/3 and their ligand DLL4 correlates with increased tumor cell viability and proliferation, suggesting the importance of the NOTCH2/3-DLL4 axis as a potential therapeutic target." (PMID 40635786, 2025). "In subcutaneous tumors of TTN-MUT and DLL4-OE 4T1 mice, therapy with the MCT4 inhibitor VB-124 decreased tumor-infiltrated MDSCs." (PMID 41326912, 2025). "DLL4-derived MDSCs promoted stemness-mediated drug resistance by inducing histone lactate modification in TNBC, suppressing the anti-tumor activities of CD8+T cells." (PMID 41326912, 2025). "M2-polarized HMC3 microglia promoted tumor angiogenesis by releasing exosomal circKIF18A, and circKIF18A bound to its target gene FOXC2 that upregulated ITGB3, CXCR4, and DLL4 expressions and activated PI3K/AKT signaling." (PMID 39781357, 2025). "The proportion of DLL4+ tumor cells was significantly higher in TNBC with poor response to neoadjuvant therapy, while the expression level of DLL4 was decreased in TNBC with good response to neoadjuvant therapy." (PMID 41326912, 2025). "DLL4 expression in GBM activates host stroma/endothelial Notch signaling, improves intratumoral vascular function, and promotes tumor growth." (PMID 38672496, 2024). "This hypoxic microenvironment triggers alternative pro-angiogenesis molecular pathways in tumor or stromal cells within the tumor microenvironment, including FGF-2, HGF, DLL4/Notch, CCL28, and others." (PMID 39075504, 2024). "The ligands DLL1, DLL4, JAG1, and JAG2 each activate Notch receptor signaling, as DLL1 and DLL4 are involved in tumor angiogenesis." (PMID 37274780, 2023). "In a phase 1a trial, navicixizumab, a bispecific antibody that inhibits DLL4 and VEGF, was tested in refractory solid tumor patients and showed the potential to inhibit tumor growth." (PMID 36900252, 2023). "Cancer cells have been demonstrated to secrete VEGF capable of inducing Dll4 in endothelial cells of the TME, which negatively regulates excessive unproductive sprouting and helps to maintain tumor angiogenesis at a steady rate." (PMID 38269089, 2023). "Tumor vasculature regularly exploits angiogenic pathways that respond to hypoxia-regulated VEGF, which in turn up-regulates DLL4 that then activates Notch signaling." (PMID 36376768, 2023). "According to the expression patterns of Dll4 and Jag1, the HCC tissues were divided into two areas (#1 and #2), which represented the peripheral and intrinsic regions of the tumor, respectively." (PMID 35064244, 2022). "In preclinical studies, dual-variable domain immunoglobulin targeting simultaneously DLL4 and VEGF (ABT-165, dilpacimab), significantly inhibited tumor growth and decreased functional tumor angiogenesis in U87-MG human GBM xenograft model." (PMID 36010607, 2022).
tumor (continued). "An attractive finding obtained from the ROC analysis was that DLL4 and EGF levels can be used to differentiate the late stages of disease from early stages, LN involvement from free LN, and high tumor size from low tumor size." (PMID 35681234, 2022). "The blocking of the Notch signaling pathway through DLL4-and VEGF acts synergistically to reduce the density and function of tumor vessels and inhibit tumor growth." (PMID 36212390, 2022). "We further evaluated the expression of DLL4 in ESM1-normal, -high, or -low expression tumor cells and found that DLL4 expression was higher in MDA-MB-231-R/E cells compared to MDA-MB-231-S and shESM1-MDA-MB-231-R cells." (PMID 36428773, 2022). "In contrast, the interaction scores of DLL4-NOTCH3, DLL1-NOTCH1, TGFBR3-TGFB1, and IGF1R-IGF1 between tumor cells and endothelial cells increased after treatment." (PMID 36474268, 2022). "In tumor models, JAG1 plays an important role in promoting sprouting angiogenesis and antagonizing DLL4-mediated Notch signaling 44-47." (PMID 35401837, 2022). "We found that endothelial-specific molecule 1 expression elevated bevacizumab-resistant tumor cells, and endothelial-specific molecule 1 further regulates MMP9, VEGF, and DLL4 to promote metastasis and angiogenesis in vitro and in vivo." (PMID 36428773, 2022). "Demcizumab (OMP-21M18) is a humanized anti-DLL4 (delta-like ligand 4) antibody that inhibits the Notch pathway and CSC activity through the inhibition of tumor growth and reduction in tumor-initiating cell frequency." (PMID 33806312, 2021). "DLL4-Notch signaling pathway interacts with several molecules and other signaling pathways, including PI3k, EGFR, and MMP9, all related to tumor invasion, proliferation, and metastasis." (PMID 36643842, 2021). "Our study in vivo highlights the importance of LY3039478 treatment as it inhibits not only the DLL4/Notch signaling but also the levels of MMP13, which promotes growth and tumor progression by degradation of the ECM." (PMID 32042099, 2020). "Analysis of tumor growth inhibition (TGI) by bioluminescent imaging verified similar TGI was observed in SSIL2Rγ- rats bearing 1806rluc+ tumors and treated by anti-DLL4-conjugated TNPs as compared to SSIL2Rγ- rats treated with control IgG-TNPs." (PMID 32373218, 2020). "Nonetheless, we cannot exclude additional, direct effects of MMP13 and the other Notch targets on tumor cells, as we showed positive immunoreactivity for HES1, DLL4, and MMP13 proteins in iCCA cells." (PMID 32042099, 2020). "Compared to age-matched controls, tumor-bearing mice have low DLL1 and DLL4 expression levels in bone marrow cells as well as low splenic T:B cell ratios." (PMID 32922403, 2020). "Analysis of tumor lysates showed reduced amounts of inflammatory and pro-angiogenic factors in HIF-1α-KD tumors, such as Cyr61 or Dll4, which correlated with a normalized vasculature." (PMID 33142239, 2020). "Numerous studies conducted in embryos, organs, and tumours have established the importance for angiogenesis of the VEGF and Dll4/Notch signalling pathways." (PMID 31043605, 2019). "Dll4 and VEGF emerge as the yin and yang of angiogenesis for embryonic vascular development and tumor angiogenesis." (PMID 32038259, 2019). "In conclusion, DLL4 has evolved an IRES element that allows the enhancement of its translation under ER stress, a condition known to be activated during tumor development when the expression of this protein is crucial." (PMID 30691003, 2019). "Previous studies have shown that productive tumor angiogenesis requires cooperation between VEGF-A, which induces proliferation of endothelial ‘tip’ cells and expression of DLL4 in ‘stalk’ cells." (PMID 31676012, 2019). "For example, heightened Dll4/Notch signaling in tumor cells can magnify TGF-β-induced pSMAD2/3 signaling and is required to sustain TGF-β-induced tumor cell growth." (PMID 29301578, 2018).